IQGAP1 (IQ motif containing GTPase activating protein 1)
Diseases named in the same sentence as IQGAP1 in open-access papers (continued):
Sharing a sentence is not in itself a finding about the gene and the disease.
cancer (continued). "This study reveals that, like IQGAP1, β-catenin also localizes to the nuclear envelope and that IQGAP1 modulates β-catenin transport to the nucleus via different domains in response to growth factor or in cancer." (PMID 32655836, 2020). "IQGAP1 is also targeted by miRNAs, and although it is a scaffolding RhoGAP that does not possess intrinsic GTPase-activating capabilities, it has been shown to function as an oncogene in cancer." (PMID 32353968, 2020). "Aberrant IQGAP1-centrosome proteins could deregulate key pathways controlled by different domains of IQGAP1 that may be co-opted by cancer cells for oncogenic development, which we find to be the case." (PMID 32655836, 2020). "Indeed, IQGAP1 is elevated at both the mRNA and protein level in a variety of cancers, and its levels correlate with aggressiveness." (PMID 32051509, 2020). "Because increased MET signaling is implicated in the development and progression of several types of carcinoma, IQGAP1 may be a potential therapeutic target in selected malignancies." (PMID 33087447, 2020). "We here show for the first time that deletion of IQGAP1 dramatically induces MEK nuclear translocation in KRAS mutant cancer cells, and that mutant KRAS could restrain MEK/β-TrCP in the cytoplasm via IQGAP1, then downregulating YAP expression." (PMID 30833665, 2019). "Next, the role of IQ3 motif in IQGAP1-mediated cancer hallmarks was examined." (PMID 31235839, 2019). "By determining the specific binding site and regulatory mechanism of each pathway scaffolded by IQGAP1, we may block the switch of the modulation role of IQGAP1 and thereby develop more efficient, novel cancer therapies." (PMID 31235839, 2019). "As an oncogene, IQGAP1 is overexpressed in certain cancers through gene amplification." (PMID 31798960, 2019). "Conversely, the distant cancer metastasis is abolished by IQGAP1 knockout in a cancer mouse model." (PMID 31640697, 2019). "One example of this is IQGAP1 removal from the site of T cell docking to cancer cells." (PMID 27880081, 2018). "Considering the clinical utility of claudin expression as a prognostic marker in variety of human cancers and the link between TJ disruption and metastatic disease, our work suggests that IQGAP1 could be a potential therapeutic target in advanced cancers." (PMID 27880081, 2018). "Targeting either the MISP/IQGAP1 or the Cdc42/IQGAP1 interaction may decrease the amount of active Cdc42 in cancer cells and thereby prevent tumor progression." (PMID 29679050, 2018). "Given the many roles of IQGAP1 and the large number of interacting partners, we focus our discussion of these functions in the context of junction formation, trafficking, growth factor signaling and cancer." (PMID 27880081, 2018). "Interestingly, disruption of epithelial architecture is a common feature of IQGAP1-overexpressing tumors, consistent with the notion that epithelial polarity cues can be hijacked by cancer cells." (PMID 27880081, 2018). "IQGAP1 is overexpressed in a variety of human cancers (reviewed in13 and30)." (PMID 29679050, 2018). "Blocking the formation of the MISP/IQGAP1/Cdc42 complex might have therapeutic potential for specific cancer types." (PMID 29679050, 2018). "However, a role for IQGAP1 and tissue plasminogen activator in trophoblast motility/invasion are yet to be characterised, but both have been shown to be key regulators of cancer motility/invasion." (PMID 30065265, 2018). "Additionally, we discuss the potential role of IQGAP1 in regulating compartmentalized signaling in polarized epithelia, the potential crosstalk between growth factor receptor signaling and TJ assembly, and the implications of IQGAP1 deregulation in cancer." (PMID 27880081, 2018). "IQGAP1 is a signaling scaffold that regulates oncogenic ERK1/2 MAPK signaling in human cancer." (PMID 28445541, 2017). "Multiple studies have investigated and identified IQGAP1 as an oncogene in different cancers." (PMID 29073199, 2017).
cancer (continued). "IQGAP1 has been identified as a marker of amplifying cancer cells in GBMs." (PMID 28098764, 2017). "Out of all 33 cancer samples, IQGAP1 and β-catenin were overexpressed (strong expression) in 36.36% and 33.33% HCTs, averagely with immunoreactivity scoring over 10, which was far more than either the overexpression level or the percentage compared with the PLTs (p<0.05)." (PMID 26252773, 2015). "Taken together, these data add support to our experimental results showing that IQGAP1 targeting to lipid raft membranes can be regulated and may contribute to cancer metastasis." (PMID 25924234, 2015). "With these five functional domains, IQGAP1 is able to bind Rac1 and Cdc42, β-catenin, E-cadherin, calmodulin and components of the mitogen-activated protein kinase pathway, all of which are involved in cancer development." (PMID 24763314, 2014). "Because IQGAP1 plays a significant role in the propagation of the MAPK signaling pathway through the RAS-RAF-MEK-ERK signaling kinase pathway involved in tumor cell proliferation and survival, IQGAP1 has been the focus of intense cancer drug development efforts." (PMID 25563226, 2014). "PKCε and PKA kinases regulate distinct signaling pathways, and while both have a role in cancer progression, their dissimilar activators and targets may also hold a key to deciphering the mechanisms behind the opposing functions of IQGAP1 and IQGAP2 in HCC." (PMID 22973521, 2012). "IQGAP1 is thought to mediate tumor cell invasion and migration in several types of cancer." (PMID 19036171, 2008). "Accumulated evidences have demonstrated that IQGAP1 may be critical for conferring invasive potential in various human cancers." (PMID 19036171, 2008). "To further investigate whether IQGAP-1 can induce cancer cell invasion and migration, we knocked down IQGAP1 using shRNA expressing plasmids controlled by U1 promoter (Clone 1, 2, 3 and 4) in HO-8910PM cells and selected by growth in the presence of puromycin." (PMID 19036171, 2008). "In addition, in vivo and in vitro validation of IQGAP1’s cancer-promoting function was done." (PMID 38546389, 2024). "The enhanced IQGAP1 membrane localization and oligomerization on the membrane surface in turn concentrates EGF pathway components to the membrane surface which may be associated with the increase EGF stimulation seen in cancer." (PMID 39357822, 2024). "Thus, the variation of the mechanistic ways that connect IQGAP1 with small GTPases could furnish cancer therapies on new foundations." (PMID 36276098, 2022). "However, the exact mechanisms of how IQGAP1 influences NK cells during cancer progression is still largely unknown." (PMID 34439095, 2021). "IQGAP1 promotes tumorigenesis in multiple cancer types, but its role in ccRCC remains unclear." (PMID 33266355, 2020). "As anoikis escape provides a selective advantage of cancer cells to distant dissemination and colonisation, our data suggest that interruption of the IQGAP1/Rac1/Src/FAK pathway might be effective for suppressing tumour growth and metastasis in chronically HBV-infected patients." (PMID 32632148, 2020). "Our results describe that IQGAP1 could regulate MEK localization in KRAS mutant cancer cells." (PMID 30833665, 2019). "The display in differential localization and quantitative expression of AmotL2, FKBP51, and IQGAP1 could be used as biomarkers for more accurate tumor staging and as potential targets for anti-cancer therapeutics by blocking or slowing down their interconnecting functions." (PMID 28441737, 2017). "IQGAP1 is not significantly mutated in any cancer type, but rather is frequently overexpressed." (PMID 28594900, 2017). "Therefore, we hypothesize that both RhoC and IQGAP1 may play important role in cancer cell transformation and proliferation and there is a potential association between them." (PMID 23145020, 2012). "We further examined the interaction between IQGAP1 and PKM2 in CD133-high and CD133-low groups to explore their relationship in cancer stemness." (PMID 40093893, 2025).
cancer (continued). "Integrin β4, relying on the regulation of TNFAIP2 and IQGAP1, effectively activated RAC1, promoting the migration of TNBC cells while enhancing the resistance of cancer cells to DNA damage-related therapies." (PMID 40830812, 2025). "Protein expression levels of AKT, IQGAP1, and MMP16 in HPV‐infected cancers and controls were determined by immunohistochemistry." (PMID 39073693, 2024). "Predominantly, IQGAP1 was highly expressed in both epithelial cancer tissues, whereas MMP16 was ubiquitously expressed in both cancers and normal tissues." (PMID 39073693, 2024). "In the current study, the association of CGN c.3560 C > T with overexpressed IQGAP1 and Rac1 activation, promoting EMT, suggests a positive correlation between IQGAP1 and Rac1 in CGN c.3560 C > T-mutant cancer cells." (PMID 38424547, 2024). "We further delved into the regulatory relationship between the overexpressed IQGAP1 and active Rac1 in CGN c.3560C > T mutant cancer cells." (PMID 38424547, 2024). "A key revelation is that CGN c.3560C > T triggers the overexpression of IQGAP1 and activates Rac1-dependent EMT, thus promoting cancer cell behavior." (PMID 38424547, 2024). "The discovery of the IQGAP1-PI3K pathway complex and the demonstration that the inhibition of IQGAP1-mediated PI3,4,5P3 production can selectively kill or block proliferation of cancer cells points to the therapeutic potential of targeting this complex." (PMID 37759697, 2023). "Genes differing insignificantly from healthy tissue were IMP-3, CDH1, IQGAP1, NEDD9, TKS5, WAS and ARPC4, indicating minimal alterations in their expression levels in the analyzed cancer samples." (PMID 37623256, 2023). "The IQ motif-containing GTPase-activating protein 1 (IQGAP1), a PI3K scaffold protein, is overexpressed in different types of cancers and moreover, it was found to be required during PI3K signaling induction by HPV16 oncoproteins." (PMID 37659653, 2023). "Meanwhile, in cancer cells, GLK directly phosphorylates and activates IQGAP1, resulting in the induction of Cdc42-mediated cell migration and cancer metastasis." (PMID 36605209, 2022). "Increased IQGAP1 and IQGAP3 levels have been found in many cancers and promote tumor growth and metastasis." (PMID 33846302, 2021). "The role of Mnk1 in cancer development has been obscure and these findings implicate it, for the first time, in the TNBC subtype downstream of IQGAP1." (PMID 32655836, 2020). "The GLK-interacting protein IQGAP1 is responsible for GLK-induced cell migration and cancer metastasis." (PMID 31640697, 2019). "IQGAP1 functions as a scaffold protein in both the PI3K-Akt and Ras-ERK pathways that are the two most prominent signaling modules regulating cancer cell proliferation and migration." (PMID 31235839, 2019). "The scaffold proteins of the Ras/MAPK pathway, including IQGAP1, KSR1, and Sur8, have essential roles in growth, transformation, and migration of cancer cells." (PMID 29383184, 2017). "Exogenous treatment with a “WW peptide,” which mimics the ERK-binding region of IQGAP1, inhibits IQGAP1/ERK binding and increased survival in murine models of RAS-driven cancers." (PMID 27221039, 2016). "The IQGAP protein family comprises three scaffold proteins, of which IQGAP1 is best characterized and known to interact with RAF, MEK and ERK and to be up-regulated in cancer." (PMID 26033452, 2015). "IQ motif-containing GTPase-activating protein 1 (IQGAP1) is known to be a negative modulator of cell–cell adhesion at adherens junctions in cancer." (PMID 38201481, 2023). "IQGAP1 and IQGAP3 were significantly elevated in cancer tissues and considered oncogenic factors; whereas, IQGAP2 was significantly decreased in cancer tissues and was considered a cancer suppressor." (PMID 36320006, 2022). "IQGAP1 is overexpressed in HCC and contributes to cancer development and advancement." (PMID 35785216, 2022).
cancer (continued). "Moreover, SPARC-like protein 1 (SPARCL1), IQGAP1, BPIFA1, and cornulin are potential candidate proteins abnormally expressed in multiple types of cancers, especially LC." (PMID 36064415, 2022). "While major studies have focused on IQGAP1, indicating an oncogenic role in most cancers, IQGAP2 has received less attention and has been described as a tumor suppressor in most cancers, including gastric cancer, prostate cancer, ovarian cancer, and breast cancer." (PMID 36362301, 2022). "PAK6, which is overexpressed in cancer and phosphorylates β-catenin, might disrupt CRC cell–cell adhesion through the PAK6/IQGAP1/E-cadherin complex at the cell junction." (PMID 34439095, 2021). "These discrepancies in the relationship between TGF-β and IQGAP1 may be due to tissue specificity or cell type specificity, or the complex roles that TGF-β signaling plays at different stages of cancer progression." (PMID 34439095, 2021). "This indicates that, though IQGAP1 is not required for liver carcinogenesis, it can still promote cancer progression in some settings." (PMID 34439095, 2021). "Another possibility is that other proteins act to maintain PI3K signaling in the absence of IQGAP1 during cancer progression." (PMID 34068608, 2021). "Upon 4NQO oral carcinogen treatment, Iqgap1−/−K14-E6E7 mice did not develop significantly less severe cancer phenotypes than the Iqgap1+/+K14-E6E7 mice." (PMID 34439095, 2021). "Sorafenib has been generally shown to have an excellent anti-tumor effect in various types of cancers including HCC, whereas IQGAP1 mediated ERK activation may interfere with its therapeutic action (Hedman, Smith & Sacks, 2015)." (PMID 33062407, 2020). "Thus, we performed KEGG pathway analysis on the candidate genes and found that IQGAP1 and VAV2 were both enriched in the “Proteoglycans in Cancer” pathway (hsa05205)." (PMID 31798960, 2019). "For instance, IQGAP1 regulates Erk1/2 phosphorylation in mouse embryonic fibroblasts and RAS-driven tumors; however, MAPK signaling occurs independently of IQGAP1 in other cancer cell lines." (PMID 29892299, 2018). "We recently described a new therapeutic strategy for Ras/MAPK-driven cancers, which does not target the core pathway members, but instead targets the interaction between IQGAP1 and ERK1/2." (PMID 28445541, 2017). "Laminin, known to promote cancer progression, may enhance tumor cell migration through activation of MCAM, IQGAP1 recruitment and subsequently myosin II retraction." (PMID 29240845, 2017). "Our previous work investigated IQGAP1 targeting in human and mouse models, but not in canine spontaneous cancer models." (PMID 28445541, 2017). "If these molecules, including IQGAP1 and other cytoskeletal components, interact with ASC in cancer cells, ASC may have a tumor suppressive role as a regulator of cytoskeletal remodeling." (PMID 27350283, 2016). "While IQGAP1 and IQGAP2 proteins share a domain structure and possess significant sequence homology, they appear to have opposing functions in vivo, at the very least in the pathogenesis of cancer." (PMID 22973521, 2012). "Additionally, IQGAP1 stimulates EGF-induced activation of the JAK-STAT pathway, a signaling module where JAK non-receptor tyrosine kinases activate STAT transcription factors to promote expression of critical mediators of cancer and inflammation." (PMID 37071417, 2023). "Notably, ARL4C and MMP14 were expressed more highly in invasive cancer cells rather than in PanIN lesions, although IQGAP1 was thoroughly expressed in tumor lesions including PanIN area." (PMID 34590580, 2021). "These events may operate downstream of IQGAP1-MAPK axis, hijacked differentially by cancer cells." (PMID 32655836, 2020). "Some studies have suggested IQGAP1 proteins are highly expressed in cancer cell lines and plays a role for scaffold protein IQGAP1 in enhancing tumorigenesis, but IQGAP1 knockout mice are viable and fertile, do not show any defects in normal epithelium and heal wounds normally." (PMID 27490120, 2016).
cancer (continued). "Furthermore, the molecular mechanisms of caveolin-1 in cancer progression have not been fully elucidated, although it likely involves modulation of lipid rafts and, based on the present data, IQGAP1." (PMID 25924234, 2015). "IQGAP1 and MMP16 mRNAs level was significantly higher in the cancers than in the NC (p < 0.05), but not AKT mRNA levels." (PMID 39073693, 2024). "mRNA expression analyses did not detect a significant alteration of IQGAP1 expression in HCC at any stage, nor was there a difference between IQGAP1 mRNA levels in cancer and normal tissue." (PMID 20977743, 2010). "Western blotting, WST-1, and colony formation assays indicated that, unlike parental cells, ectopic ARF1 expression could not increase p-ERK expression or cell proliferation in IQGAP1-knockout HCT116 and RKO cells, suggesting that IQGAP1 was essential for the ARF1 function in cancer." (PMID 33408784, 2021).